KDM6B (lysine demethylase 6B)
Diseases named in the same sentence as KDM6B in open-access papers (continued):
Sharing a sentence is not in itself a finding about the gene and the disease.
osteoporosis (2 papers, 2021 to 2023). A condition of reduced bone mass, with decreased cortical thickness and a decrease in the number and size of the trabeculae of cancellous bone (but normal chemical composition), resulting in increased fracture incidence. "Taken altogether, miR‐15b inhibits osteoblast differentiation and autophagy to aggravate osteoporosis by targeting USP7 to regulate KDM6B expression." (PMID 33434305, 2021). "We established osteoporosis models through ovariectomy and determined that miR‐15b was highly expressed whereas USP7 and KDM6B were poorly expressed in tissue of osteoporosis mice." (PMID 33434305, 2021). "To identify the in vivo interaction among miR‐15b, USP7 and KDM5B, we established models of osteoporosis mice and treated them with injection of miR‐15b agomir + oe‐NC, agomir‐NC + oe‐NC and miR‐15b agomir + oe‐KDM6B." (PMID 33434305, 2021). "It is found that KDM6B was significantly poorly expressed in osteoporosis through microarray data analysis in GEO database." (PMID 33434305, 2021). "RT‐qPCR and Western blot analysis revealed that KDM6B expression decreased in osteoporosis mice (P < .05)." (PMID 33434305, 2021). "Thus, it can be concluded that miR‐15b overexpression suppressed osteoblast differentiation and autophagy to aggravate osteoporosis by suppressing USP7/KDM6B axis." (PMID 33434305, 2021). "Knockdown of KDM6B significantly suppresses osteogenic differentiation to aggravate the osteoporosis, suggesting that KDM6B may present as therapeutic targets for promoting osteoblast differentiation and lead to clues for new treatment in osteoporosis." (PMID 33434305, 2021). "In conclusion, our study demonstrated that up‐regulation of miR‐15b could inhibit the expression of USP7, which potentially suppress the osteoblast proliferation, differentiation and autophagy to aggravate osteoporosis through inhibition of KDM6B expression." (PMID 33434305, 2021). "In addition, more studies are required in order to adequately define the detailed mechanisms by which miR‐15b interacts with USP7 and KDM6B and influences osteoporosis progression." (PMID 33434305, 2021). "Western blot analysis showed reduced protein levels of Runx2, osterix, LC3II/I and elevated P62 protein level in osteoporosis mice injected with miR‐15b antagomir, while the results were opposite in osteoporosis mice injected with miR‐15b antagomir and expression vectors containing KDM6B (P < .05)." (PMID 33434305, 2021). "Therefore, the obtained data suggested that USP7 could induce osteoblast differentiation and autophagy to ameliorate osteoporosis by increasing KDM6B expression." (PMID 33434305, 2021). "Moreover, osteoporosis mice injected with miR‐15b agomir exhibited reduced BMD, maximum elastic stress and maximum load, while osteoporosis mice injected with miR‐15b antagomir and expression vectors containing KDM6B revealed increased BMD, maximum elastic stress and maximum load." (PMID 33434305, 2021). "However, the effects of miR‐15b regulating KDM6B by targeting USP7 on osteoporosis remain unclear." (PMID 33434305, 2021). "In this study, we found that USP7 enhanced the stability of KDM6B to promote KDM6B expression inhibited the ubiquitination, while miR‐15b inhibits USP7 expression in osteoporosis." (PMID 33434305, 2021). "Of note, our data revealed that inhibition of proteasome up‐regulated expression of USP7 and KDM6B, while increased USP7 expression promoted osteoblast differentiation and autophagy, alleviating osteoporosis." (PMID 33434305, 2021).
pancreatic ductal adenocarcinoma (2 papers, 2018 to 2019). An infiltrating adenocarcinoma that arises from the epithelial cells of the pancreas. "Loss of KDM6B resulted in more aggressive pancreatic ductal adenocarcinoma." (PMID 31036064, 2019). "On the contrary, KDM6B also promoted an epithelial-like phenotype, since, in the pancreatic ductal adenocarcinoma cell line BxPC3 and in xenograft models, KDM6B directly induced the demethylation of the H3K27me3 mark on the CEBPA promoter and induced the expression of this gene." (PMID 34991274, 2018).
Salmonella Infections (2 papers, 2021 to 2025). Infections with bacteria of the genus SALMONELLA. "Together these data differentiate KDM6B activation from its demethylase activity in the context of Salmonella infection, and reveal requirement of SPI1 effector(s) in this process." (PMID 34696686, 2021). "Together these data led us toconclude that Salmonella infection results in increased expression of KDM6B and a concomitant lowering of H3K27me3 mark in the host." (PMID 34696686, 2021). "The observed KDM6B upregulation was followed with a decrease in the host H3K27me3 during Salmonella infection." (PMID 34696686, 2021). "To identify such target genes of KDM6B upon Salmonella infection, we carried out Chromatin immunoprecipitation coupled with RT-PCR array (hereafter ChIP-qPCR array)." (PMID 34696686, 2021). "The current study reveals a role for KDM6B, a host demethylase, in epigenetic remodeling of specific gene loci in host macrophages enabling establishment of chronic Salmonella infections." (PMID 34696686, 2021). "KDM6B upregulation, at 4 h post Salmonella infection, was also seen in intestinal epithelial cell line CaCo2, murine macrophage cell line RAW264.7 and primary bone marrow derived macrophages (BMDMs)." (PMID 34696686, 2021). "In the current study we identified, histone H3-lysine 27 trimethylation (H3K27me3)-specific demethylase, KDM6B to be upregulated in both cell culture and in murine model of Salmonella infection." (PMID 34696686, 2021). "Together these data implied that Salmonella-mediated KDM6B upregulation and its demethylase activity was required for polarization of macrophages and thus establishing chronic Salmonella infection." (PMID 34696686, 2021). "Among the epigenetic modifier genes that were screened for, only KDM6B expression was found to be upregulated (>3 fold) in response to Salmonella infection." (PMID 34696686, 2021). "We demonstrate that upon Salmonella infection KDM6B upregulation is followed by a concomitant decrease in overall H3K27me3 mark of host, which required Salmonella SPI1 effectors." (PMID 34696686, 2021). "In addition, GSKJ4-mediated KDM6B inhibition in chronic Salmonella infection mice model also displayed a reduced CD301 expressing macrophage population in MLN and splenic tissues." (PMID 34696686, 2021). "The cells were further analyzed for fatty acid oxidation gene expression to determine whether KDM6B perturbations also affect the macrophage metabolic environment during Salmonella infection." (PMID 34696686, 2021). "KDM6B was knocked down in RAW264.7 cells (KDM6BKD) and CFU post Salmonella infection at 4 h and 18 h was estimated using GPA and compared with mock treated RAW264.7 cells (Cont-siRNA)." (PMID 34696686, 2021). "Furthermore, KDM6B-perturbed BMDMs also showed impaired expression of other M2 marker genes and fatty acid oxidation pathway genes upon Salmonella infection, indicating compromised Salmonella infection-mediated M2 polarization and fatty acid oxidation pathway upon KDM6B inhibition." (PMID 34696686, 2021). "While, si-RNA-mediated KDM6B knockdown or GSKJ4 treatment of cells showed reduced or no up regulation of PPARδ upon 18 h post Salmonella infection." (PMID 34696686, 2021). "Increased expression of KDM6B upon Salmonella infection was not dependent on live bacteria, as even heat killed Salmonella (HKS) was capable of triggering similar response suggesting a PAMP-mediated mechanism." (PMID 34696686, 2021).
squamous cell carcinoma (2 papers, 2021 to 2022). A carcinoma arising from squamous epithelial cells. "In squamous cell carcinoma, KDM6B is repressed by the transcription factor CSL, contributing to tumor proliferation, occurrence, and correlated inflammation." (PMID 35783266, 2022).
type 2 diabetes (2 papers, 2022 to 2024). "Moreover, KDM6B is implicated in metabolic disorder-related diseases, including type 2 diabetes and NASH." (PMID 35100965, 2022).
allergic disease (1 paper, 2025). An immune response that occurs following re-exposure to an innocuous antigen, and that requires the presence of existing antibodies against that antigen. "The inhibition of KDM6B activity in monocytes may be the therapeutic target of HDM-allergic diseases." (PMID 40503225, 2025). "Selective inhibition of KDM6B activity and monocyte inflammatory response may be a therapeutic target in recurrent HDM-allergic diseases." (PMID 40503225, 2025).
benign prostate hyperplasia (1 paper, 2021). "The average KDM6B expression is limited in benign prostate hyperplasia, upregulated in PCa, and even higher in metastatic PCa25." (PMID 33414463, 2021).
brain tumors (1 paper, 2021). "In brain tumors, global loss of H3K27me3 may be explained by KDM6B over-expression, leading to H3K27me3 demethylation, and/or EZHIP over-expression that leads to inhibition of EZH2, resulting in global loss of H3K27me3." (PMID 34399838, 2021). "Loss of H3K27me3 has been shown in pediatric brain tumors and may be influenced by overexpression of the PRC2 inhibitory protein EZH Inhibitory Protein (EZHIP) and/or KDM6B, an H3K27me3 demethylase." (PMID 34399838, 2021).
cleft palate (1 paper, 2022). Cleft palate is a fissure type embryopathy that affects the soft and hard palate to varying degrees. "Loss of Kdm6b in cranial neural crest (CNC)-derived cells results in cleft palate." (PMID 35212626, 2022).
cocaine addiction (1 paper, 2017). "We found Kdm6b, a histone demethylase, increased 7d after cocaine withdrawal, indicating its potential role in cocaine addiction for the first time." (PMID 28386228, 2017).
Cognitive impairment (1 paper, 2022). Abnormal cognition is characterized by deficits in thinking, reasoning, or remembering. "Besides impaired sociability, some patients with KDM6B mutations have language delay, motor-skill delay, and cognitive impairment as their main clinical manifestations." (PMID 35711692, 2022).
craniosynostosis (1 paper, 2020). Craniosynostosis is defined as the premature fusion of one or more cranial sutures leading to secondary distortion of skull shape resulting in skull deformities with a variable presentation. "In this study, we demonstrate for the first time that the histone demethylases, Kdm6a, and Kdm6b have the potential to be used as novel therapeutic targets for the prevention of craniosynostosis in an SCS mouse model, where the Twist-1 gene is mutated." (PMID 33298158, 2020). "Collectively, our findings provided evidence that Kdm6a and Kdm6b are putative targets in treating craniosynostosis in Twist-1del/+ mutant mice and confirmed previous studies that deregulated epigenetic patterns play significant roles in the development of craniosynostosis." (PMID 33298158, 2020). "The inhibition of Kdm6a and Kdm6b activity by GSK-J4 could be used as a potential non-invasive therapeutic strategy for preventing craniosynostosis in children with SCS." (PMID 33298158, 2020).
dysplasia (1 paper, 2021). A usually neoplastic transformation of the cell, associated with altered architectural tissue patterns. "In more recent studies, overexpression of KDM6B in transgenic mice let to a mild hematopoietic phenotype with features of MDS and CMML, including dysplasia, leukopenia, and an impaired repopulation capacity of HSPCs." (PMID 34944554, 2021).
ependymoma (1 paper, 2022). A WHO grade II, slow growing tumor of children and young adults, usually located intraventricularly. "For instance, the hypoxic metabolism of posterior fossa A ependymoma generates intermediary products that favor higher levels of H3K27ac (acetyl-CoA) and lower levels of H3K27me3 (α-ketoglutarate, which stimulates the activity of the H3K27 demethylases KDM6A and KDM6B)." (PMID 36371348, 2022).
epilepsy (1 paper, 2024). A brain disorder characterized by episodes of abnormally increased neuronal discharge resulting in transient episodes of sensory or motor neurological dysfunction, or psychic dysfunction. "Notably, URVs in KDM6B associated with epilepsy were exclusively missense (MPC ≥2), whereas KDM6B variants implicated in DDs were predominately protein-truncating." (PMID 36865150, 2024).
Ewing sarcoma (1 paper, 2025). A small round cell tumor that lacks morphologic, immunohistochemical, and electron microscopic evidence of neuroectodermal differentiation. "To understand whether the function of KDM6B in Ewing sarcoma cells is associated with its demethylase activity, we investigated the H3K27me3 dynamics in KDM6B-depleted cells." (PMID 41085408, 2025). "The differential location and partnership identified for each of the KDM6 demethylases in Ewing sarcoma suggest that KDM6B specifies EWSR1::FLI1 for the most active regions and KDM6A signals for a specific set of enhancers that commit to neural lineage." (PMID 41085408, 2025). "In this study, we shed light on the dynamics of H3K27me3 removal by KDM6A and KDM6B demethylases within the context of Ewing sarcoma." (PMID 41085408, 2025). "To gain insight into the role of both demethylases on the EWSR1::FLI1 transactivation activity, we knocked down KDM6A and KDM6B in two Ewing sarcoma cell lines, A-673 and TC-71, using a doxycycline-inducible system." (PMID 41085408, 2025). "Although KDM6A expression was similar across tumor types, KDM6B was expressed at higher levels in Ewing sarcoma cell lines than in other sarcomas." (PMID 41085408, 2025). "Analysis of KDM6A and KDM6B by IHC in 43 Ewing sarcoma primary tumor specimens from newly diagnosed patients at our institution revealed that both demethylases were highly expressed by semiquantitative H-score analysis." (PMID 41085408, 2025). "Taken together, gene expression data and IHC studies indicate that KDM6A and KDM6B are highly expressed in Ewing sarcoma cell lines and primary tumor samples." (PMID 41085408, 2025). "All these data confirm the role of KDM6B in the maintenance of Ewing sarcoma tumorigenesis." (PMID 41085408, 2025). "KDM6B expression in Ewing sarcoma tumors was particularly high compared with other sarcomas." (PMID 41085408, 2025). "As KDM6B KO reduces the expression of important targets for Ewing sarcoma tumorigenesis, we tested whether its depletion interferes with tumor growth." (PMID 41085408, 2025). "The intersection obtained in A-673 was validated in a second Ewing sarcoma cell line, TC-71, in which we found 1,163 common peaks between EWSR1::FLI1 and KDM6A/KDM6B (P value < 0.05; FDR <10−5 in all cases)." (PMID 41085408, 2025). "Among the Ewing sarcoma cell lines, the expression of KDM6A was similar in cell lines containing EWSR1::ERG compared with those containing EWSR1::FLI1, whereas KDM6B showed higher levels in those with EWSR1::FLI1." (PMID 41085408, 2025). "Although, in hpMSCs, overexpression of EWSR1::FLI1 remodels the chromatin landscape by redistributing H3K27me3, in Ewing sarcoma cell lines, depletion of KDM6B—but not KDM6A—exerts its main effects partly by restoring H3K27me3 levels at enhancers." (PMID 41085408, 2025). "Furthermore, IHC analysis of tumors confirmed the expression of the Ewing sarcoma marker CD99 and reduced levels of KDM6B and Ki-67." (PMID 41085408, 2025). "To shed light on whether KDM6A and KDM6B demethylases are involved in H3K27me3 to H3K27ac switches in enhancers regulated by EWSR1::FLI1, we carried out ChIP-seq for KDM6A, KDM6B, and EWSR1::FLI1 in the Ewing sarcoma cell line A-673." (PMID 41085408, 2025). "KDM6A and KDM6B mediate critical mechanisms behind EWSR1::FLI1 transcriptional activation program involving demethylase-independent and dependent functions, respectively, supporting the development of therapeutic strategies targeting these demethylases in Ewing sarcoma." (PMID 41085408, 2025). "Moreover, when we treated Ewing sarcoma cells with the KDM6A/KDM6B demethylase inhibitor GSK-J4, we found that the expression of EWSR1::FLI1-activated targets decreased strongly in those targets containing only KDM6B, suggesting that GSK-J4 phenocopies expression changes induced by KDM6B deletion." (PMID 41085408, 2025).
hearing disorder (1 paper, 2023). A disorder characterized by the partial or complete loss of the ability to detect sounds due to damage to the ear structures or inability of the brain to properly interpret or process the auditory signals it receives from the anatomic structures of the ear. "Since histone methylation and demethylation are reversible, targeting Kdm6b may present as a novel therapeutic regimen for hearing disorders." (PMID 34716527, 2023).
intestinal tumor (1 paper, 2022). "Collectively, these results suggested that Kdm6b-dependent IELs play a role in intestinal tumor surveillance and emphasized the important contribution of Kdm6b to the cytotoxicity of TCRαβ+CD8αα+ IELs." (PMID 34999729, 2022).
ischemia (1 paper, 2022). A hypoperfusion of the BLOOD through an organ or tissue caused by a PATHOLOGIC CONSTRICTION or obstruction of its BLOOD VESSELS, or an absence of BLOOD CIRCULATION. "miR-22-3p ameliorated ischemia/reperfusion injury, decreased neuronal apoptosis, inhibited effects of KDM6B histone demethylase." (PMID 36361891, 2022).
metastasis (1 paper, 2022). The spread or migration of cancer cells from one part of the body (where they first appeared) to another. "In tumorigenesis, KDM6B induced an epithelial−mesenchymal transition and lymph node metastasis in KIRC." (PMID 35783266, 2022).
metastatic cancer (1 paper, 2022). A carcinoma which has spread from the original site of growth to another anatomic site. "Furthermore, a positive correlation of the gene expression from two different metastatic cancer data suggesting the involvement of KDM6B in regulating HIF1α, SOX2, and CD44 further indicates the stemness regulatory function of KDM6B in various cancer types." (PMID 35186918, 2022).
motor neuron diseases (1 paper, 2024). "Our study reveals GEMIN5 regulates Kdm6b expression with implications for motor neuron diseases and therapy." (PMID 39337533, 2024). "In conclusion, our study reveals the RNA-binding protein GEMIN5 to regulate Kdm6b gene expression with implications for motor neuron diseases and therapy." (PMID 39337533, 2024). "Beyond motor neuron disease mechanisms, it reveals a role for GEMIN5 in the regulation of the epigenetic enzyme KDM6B expression and consequently, enabling the expression of KDM6B-Isl1-Lxh3 target gene HB9, which consolidates motor neuron identity." (PMID 39337533, 2024). "Further study is needed to assess pathways upstream and downstream of KDM6B that may yield neuroprotective targets for SMA and other motor neuron diseases." (PMID 39337533, 2024). "The functional importance of KDM6B for neuroprotection was not previously explored in SMA and other motor neuron diseases." (PMID 39337533, 2024).
nutritional deficiency (1 paper, 2023). "Under nutritional deficiency, fibroblast growth factor-21 (FGF21) signaling activates the global expression of autophagy-related genes through the histone H3K27-ME3 demethylase Jumonji-D3 (JMJD3/KDM6B), thus mediating lipid degradation." (PMID 37762347, 2023).
ovarian serous cystadenocarcinoma (1 paper, 2022). A malignant serous cystic epithelial neoplasm arising from the ovary. "In KIRC (kidney renal clear cell carcinoma) and OV (ovarian serous cystadenocarcinoma), the KDM6B level was significantly associated with the pathological stage." (PMID 35783266, 2022).
ovarian tumor (1 paper, 2018). "Moreover, we have shown that KB9520-activated ERβ has a strong stimulatory effect on KDM6B expression, that most likely add to the ERβ-mediated ovarian tumor inhibitory activity." (PMID 29422491, 2018).
parasitic infection (1 paper, 2017). "Other work in mouse macrophages showed that KDM6B can be upregulated by IL-4 in a STAT-6-dependent manner and that it is essential for IL-4 induced polarization in vitro and in response to certain kinds of parasitic infection in vivo." (PMID 28228757, 2017).